IDH1 (isocitrate dehydrogenase (NADP(+)) 1)
Diseases named in the same sentence as IDH1 in open-access papers (continued):
Sharing a sentence is not in itself a finding about the gene and the disease.
cholangiocarcinoma (continued). "AG-120, also known as Ivosidenib, is a potential candidate for various IDH1 mutants and the only inhibitor which successfully entered into the phase III level of various clinical tests including Cholangiocarcinoma, Leukemia, Acute Myeloid Cancer, and solid tumors." (PMID 36903561, 2023). "Efficacy was seen in four out of six IDH1/2-mutant mesenchymal sarcomas, but no clinical benefit was seen in four patients with IDH1/2-mutant cholangiocarcinomas." (PMID 34027408, 2021). "Alterations in chromatin remodeling genes (ARID1A, BAP1, IDH1, IDH2, PBRM1, SMARCB1) were found in 30.7% (47/153) of cancers in our series, confirming recent reports on the significant involvement of these genes in cholangiocarcinoma." (PMID 24867389, 2014). "Although the resistance to anti-IDH1/2 drugs was observed in cholangiocarcinoma and could represent an obstacle to the long-term treatment of patients with IDH inhibitors, this problem may be overcome by the use of dual inhibitors (targeting both IDH1 and IDH2), which are currently under evaluation." (PMID 39123479, 2024).
brain tumors (164 papers, 2009 to 2026). "BT142 is the first brain tumor cell line with an endogenous IDH1 mutation and detectable 2-HG production both in vitro and in vivo." (PMID 39768176, 2024). "Utilizing live analysis of nanopore sequencing data, we evaluated the brain tumor-associated molecular markers IDH1 R132, IDH2 R172, pTERT C228 and C250, H3F3A K27 and G34, Hist1H3B K27, and BRAF V600." (PMID 39606159, 2024). "Brain tumors harboring mutations in genes IDH1 or IDH2 can be identified by DESI-MS due to the accumulation of the oncometabolite 2-hydroxyglutarate (2-HG)." (PMID 39595159, 2024). "This shows that brain tumor patients with the IDH1 mutation are at a lower risk of VTE, while the risk in patients with IDH1 wild-type tumors is strongly linked to PDPN expression levels." (PMID 39682237, 2024). "Other examples include diagnostic utility of CTNNB1 mutations in pediatric desmid tumors and IDH1/2 mutations in brain tumor subtypes." (PMID 37483495, 2023). "Studies indicate brain tumors harboring the IDH1 mutation offer a median overall survival of 3.8 years compared to 1 year for patients with wild-type IDH1." (PMID 37733671, 2023). "Molecular alterations assessed in brain tumors include IDH1/2 mutations, Histone H3F3A mutation, MGMT promoter methylation, TERT promoter methylation, EGFR amplification, ATRX retention or loss, and 1p/19q chromosomal co-deletion, for example." (PMID 37189838, 2023). "Immunohistochemistry (IHC) represents a common methodology for the direct detection of the most common IDH1 mutation in brain tumors, IDH1 p.R132H." (PMID 36360312, 2022). "We describe a novel DNA methylation epi-signature that specifically distinguishes brain tumors having oncogenic IDH1/IDH2 variants from tumors with normal IDH1/IDH2." (PMID 36360312, 2022). "Using radiogenomic approaches on brain tumor MRI images, IDH1 mutations have been accurately predicted in several articles making this a veritable alternative to biopsy." (PMID 35454365, 2022). "Despite IDH1 mutations and hormone receptor expression being good prognostic factors, recurrence of brain tumor patients with IDH1 mutations and breast cancer patients with hormone receptor expression is frequently observed in the clinical setting." (PMID 32335823, 2020). "Matrix assisted laser desorption/ionization - time-of-flight analyses detected r-2HG within the 0.8–11 mM range in 4-μm frozen slices of brain tumors containing IDH1/2 mutations, whereas 0.2–0.4 mMr-2HG was detected in wt tumor tissue slices." (PMID 31847543, 2020). "As mentioned, the existence of IDH1/2 mutations is an important marker in brain tumor diagnosis and prognosis." (PMID 32993063, 2020). "Mutations in IDH1 are often the first hit in the development of diffuse gliomas, suggesting IDH1 mutations as key events in the formation of these brain tumors." (PMID 33081688, 2020). "Concentrations of 1.7–2.6 mM 2HG were estimated, using combined 900 MHz 1H- and 13C-NMR analyses of extracts from IDH1-mutated brain tumor tissues." (PMID 31847543, 2020). "Isocitrate dehydrogenase 1 and 2 (IDH1/2) mutations are also frequent in several types of cancer, especially in a number of brain tumors." (PMID 33333852, 2020). "Analysis of the 20S proteasome ChT-L activity in brain tumor patients depending on the IDH1 mutation found that IDH1 wild-type individuals had statistically higher proteasome activity compared to IDH1 mutants (p = 0.0261)." (PMID 32886667, 2020). "The aim of this study is to investigate the prevalence of IDH1105GGT in a cohort of brain tumors, and its association with clinicopathologic features and IDH1 and IDH2 missense mutations." (PMID 29535392, 2018). "Other than brain tumor or hematologic malignancies, intrahepatic cholangiocarcinoma (iCC) is a well-known solid tumor with IDH1 mutation (6.8–20%)." (PMID 28403884, 2017).
brain tumors (continued). "Here, we demonstrated for the first time, that fast Cold-PCR can be successfully used to enrich the mutated form of IDH1 in DNA sequences from peripheral blood EVs isolated from brain tumor patients." (PMID 27902458, 2017). "We show that a conformation-specific Fab can reactivate an IDH1 mutant associated with brain tumors." (PMID 28373671, 2017). "Taken together, identifying critical gene mutations in brain tumors is gaining clinical relevance as, for example IDH1 and IDH2 mutations bear predictive and prognostic preposition." (PMID 27454254, 2016). "Other brain tumors harboring IDH1 mutations with moderate frequency include gangliogliomas, giant cell glioblastomas, and primitive neuroectodermal tumors, although only small numbers of these tumors have been studied." (PMID 26858939, 2016). "Mutations in isocitrate dehydrogenase 1 and 2 (IDH1/2) are frequently found in brain tumors, and the resulting onco–metabolite, 2–hydroxyglutarate (2HG), has been suggested to be a potential diagnostic and prognostic biomarker of the diseases." (PMID 26820720, 2016). "Tam-Idh1-KI mice also expressed high levels of genes associated with IDH1-mutant human brain tumors." (PMID 27693047, 2016). "Recently, aberrant methylation of MLH1, MGMT and MSI were shown to be associated with mutations in genes such as BRAF, RAS and IDH1 in colon and brain tumours." (PMID 23414134, 2013). "In brain tumors, the best evidence that metabolic enzymes play a causative role comes from the discovery of the IDH1 and IDH2 mutations." (PMID 23229761, 2013). "Moreover, the recent success of the INDIGO clinical trial on AG-881 (vorasidenib®), an aminotriazine-based mutated IDH1/2 inhibitor (IC50 = 6 nM/12 nM), validated the need for noninvasive detection of mIDH1 in brain tumors." (PMID 42198334, 2026). "Finally, IDH inhibitors also find space in brain tumors as well as in the hematological field (acute myeloid leukemia with IDH1/2 mutation) and in that of advanced cholangiocarcinoma." (PMID 38273856, 2023). "The identification of IDH1/2 mutations in diffuse gliomas represents, doubtless, one of the major breakthroughs in the field of neuro-oncology over the last decades, which led brain tumors into a new molecular era, with several significant diagnostic, prognostic, and therapeutic implications." (PMID 35267433, 2022). "Another study indicated that IDH1/2 mutations represent early events in brain tumor formation." (PMID 33980169, 2021). "We also examined the ability of attenuated total reflection (ATR)-FTIR spectroscopy in detecting the biomolecular events and global epigenetic and metabolic changes associated with mutations in the IDH1 enzyme, in blood serum samples collected from an additional 72 brain tumour patients." (PMID 33302429, 2020). "The study indicates that IDH1/2 mutations represent early events in brain tumor formation." (PMID 33489866, 2020). "Given the significant biological differences between IDH1‐mutated and IDH1 wild‐type brain tumors, whether this can be extended to other combinations of cancer types and somatic driver events remains to be seen." (PMID 32239503, 2020). "We then asked whether oncogenic IDH1 might be associated with markers of mTOR activation in human brain tumours." (PMID 27624942, 2016). "Interestingly, the primary mutation found in IDH1 brain tumours was at codon R132, while in thyroid carcinomas, non-R132 mutations were found." (PMID 23414134, 2013). "However, the IDH1 R132H mutations is by far the most prevalent IDH1/2 mutation found in brain tumors, making up 89% of all mutations." (PMID 22829908, 2012). "If IDH loss-of-function alone is critical for tumourigenesis, we might expect IDH3 mutations to occur in brain tumours, including those sub-types with relatively low frequencies of IDH1 and IDH2 mutations." (PMID 21625441, 2011).
brain tumors (continued). "Interestingly, the IDH1 mutation in primary brain tumours is linked to better survival." (PMID 34854890, 2021). "By contrast, another recent report has shown that mutant IDH1 proteins exhibit a gain-of-function phenotype by generating R-2-hydroxyglutarate (2HG), a toxic metabolite associated with an increased risk of malignant brain tumours in patients with inherited errors of 2HG metabolism." (PMID 25147764, 2014). "Since IDH1 mutation is associated with prolonged survival and better response to chemotherapy, 1H-MRS is highly informative for these subtypes of brain tumors." (PMID 39728759, 2024). "Out of 135 brain tumor samples tested, 28 (20.7%) had one clinically relevant variant, 11 (8.1%) had a BRAF Val600Glu variant, 14 (10.3%) had an IDH1 Arg132 variant, and 3 (2.2%) had an IDH2 Arg172 variant." (PMID 37483495, 2023). "In brain tumors such as GBM, mutations of IDH1 are commonly correlated with more prolonged survival." (PMID 36830847, 2023). "IDH1 wild-type tumors are often observed in patients with advanced brain tumors and are often associated with larger tumor volume, lower KPS, and worse clinical outcomes than patients with IDH1 mutations." (PMID 37917280, 2023). "We started by focusing on the genes known to be altered in GB IDH1-WT, referring to two databases: my cancer genome–MCG, mycancergenome.org and American Brain Tumor Association (ABTA), abta.org." (PMID 33922652, 2021). "A phase I clinical trial at Duke University is ongoing in which the intradermal IDH1 peptide vaccine is tested in IDH1-positive grade II primary brain tumors (ClinicalTrials.gov identifier: NCT02193347)." (PMID 33767690, 2020). "We also found that brain tumor IDH1 wild-type individuals had statistically higher ChT-L proteasome activity compared to IDH1 mutants." (PMID 32886667, 2020). "Based on these findings, we propose that the combination of H2AFJ levels with MGMT and/or IDH1 features is likely able to more precisely identify brain tumor patients who will have good outcomes after TMZ therapy." (PMID 31906036, 2019). "In the clinical brain tumor tissues, carnitine and acyl-carnitine were reduced strikingly in the IDH1 mutant group, indicating suppression of β-oxidation." (PMID 31278288, 2019). "We analyzed 26 brain tumor samples with known IDH1 or IDH2 mutation and compared readouts to those from 28 brain tumor samples of wildtype IDH status." (PMID 29499756, 2018). "Patients with wild‐type IDH1 brain tumors and high podoplanin expression had a significantly increased VTE risk compared with those with mutant IDH1 tumors and no podoplanin expression (6‐month risk 18.2% vs. 0%)." (PMID 29676036, 2018). "All brain tumors that expressed podoplanin to a medium‐high extent showed also an IDH1 wild‐type status." (PMID 29676036, 2018). "Independent studies revealed that podoplanin expression in brain tumors is associated with increased VTE risk, whereas the isocitrate dehydrogenase 1 (IDH1) mutation is associated with very low VTE risk." (PMID 29676036, 2018). "Although brain tumor patients with IDH1 mutation are at very low risk of VTE, the risk of VTE in patients with IDH1 wild‐type tumors is strongly linked to podoplanin expression levels." (PMID 29676036, 2018). "This study evaluates the presence of R132H mutation in isocitrate dehydrogenase (IDH1) gene and the vascular endothelial growth factor (VEGF) +936 C/T polymorphism in brain tumors." (PMID 28948065, 2017).
brain tumors (continued). "The prevalence of mutant isocitrate dehydrogenase 1 (IDH1) brain tumors has generated significant efforts to understand the role of the mutated enzyme product d-2-hydroxyglutarate (D2HG), an oncometabolite, in tumorigenesis, as well as means to eliminate it." (PMID 27781195, 2016). "Frequency and/or type of mutations in genes encoding isocitrate dehydrogenase 1 (IDH1), isocitrate dehydrogenase 2 (IDH2), and epidermal growth factor receptor (EGFR) vary between histological types of primary brain tumors." (PMID 27454254, 2016). "Our mice provide insights into human IDH1-driven brain tumors and a model system for assessing therapies." (PMID 27693047, 2016). "Patients with mutant IDH1 brain tumors are prevalent with a number of investigations describing the biological and biochemical effects of the oncometabolite, D2HG, which is produced in high quantities." (PMID 27781195, 2016). "We showed that CSF ctDNA is more representative of brain tumour genomic alterations than plasma and putative actionable gene mutations and CNA (that is, EGFR, PTEN, ESR1, IDH1, ERBB2, FGFR2) can be identified." (PMID 26554728, 2015). "The results indicated a correlation between PDPN expression and IDH1 status in brain tumors." (PMID 39682237, 2024). "By carrying out Pearson’s correlation analysis between the expression levels of MCT1 and IDH1 in brain tumors, we highlighted that, in GBM patients, the expression levels of these two genes were significantly closely inversely correlated (r = −0.4163, p < 0.0001)." (PMID 35574309, 2022). "For static acquisitions, we induced 24 IDH1+ and 28 IDH1– rat brain tumors." (PMID 35303961, 2022). "A recent drug screening also identified a class I HDAC inhibitor, Vorinostat, as an inducer of ferroptosis in small cell lung cancer (SCLC) and isocitrate dehydrogenase (IDH1/2)-mutant brain tumors, suggesting an unique vulnerability that is regulated by histone or non-histone acetylation." (PMID 35174081, 2022). "MGMTp methylation and IDH1 mutations do not affect [18F] FDOPA uptake in primary brain tumors and therefore cannot be assessed or predicted by radiopharmaceutical uptake parameters." (PMID 33066633, 2020). "Interestingly, the amount of all 20 amino acids including essential amino acids was reduced in IDH1 mutant brain tumors and IDH1R132H-expressing U87 cells." (PMID 31278288, 2019). "Some reports have demonstrated that mutations in IDH1 and IDH2 are recurrent in brain tumors." (PMID 29312565, 2017). "Similarly, we did not detect a difference in 5hmC levels between tumors that were immunoreactive or immunonegative for the IDH1 mutant R132H within multiple brain tumor types." (PMID 22829908, 2012). "A total of 68 brain tumors were assessed for IDH1 and IDH2 promoter methylation status." (PMID 23267435, 2012). "In brain tumors, 5hmC levels were high in low grade tumors and reduced in malignant glioma, but did not exhibit any correlation with IDH1 mutation status." (PMID 22829908, 2012). "Cy-TOF of surgical resections have characterized the lymphocyte landscape in primary and secondary brain tumor entities.Compared to primary brain tumors, metastases favor T and B cell infiltration and T regulatory cells (T regs) present higher accumulation in brain metastasis and IDH1 wt gliomas." (PMID 34540682, 2021).